Y_RNA (Y RNA )
Gene: Miscellaneous RNA gene on chromosome 6 (7,187,582 to 7,187,686, reverse strand). Ensembl gene ENSG00000201483.
Homologues: Orthologues: chimpanzee Y_RNA (94% identical), macaque Y_RNA (90% identical). Paralogues in human: Y_RNA (86% identical), Y_RNA (84% identical), Y_RNA (83% identical), RNY1 (82% identical), RNY1P11 (81% identical), RNY1P8 (81% identical), Y_RNA (81% identical), Y_RNA (80% identical), RNY1P7 (79% identical), Y_RNA (79% identical), Y_RNA (78% identical), Y_RNA (77% identical), and 94 more.